HIF1A (hypoxia inducible factor 1 subunit alpha)
Diseases named in the same sentence as HIF1A in open-access papers (continued):
Sharing a sentence is not in itself a finding about the gene and the disease.
bladder cancer (continued). "Little has been reported specifically for human bladder cancer, aside from a study showing macrophage infiltration positively correlated with HIF1α expression, angiogenesis, and a poor prognosis." (PMID 37240301, 2023). "The expression of ZEB1 and HIF-1α in bladder cancer tissues was significantly higher than in normal bladder tissues." (PMID 37627900, 2023). "We found that MI efficiently inhibits bladder cancer progression both in vitro and in vivo by deactivating the Nox 4/NF-κB/HIF-1α signaling pathway via upregulating miR-26b expression." (PMID 35293283, 2022). "HIF1A is both a bladder cancer driver and a potential drug target identified by our drug mapping studies." (PMID 35035776, 2022). "Our recent studies show that sulforaphane inhibits bladder cancer cell proliferation via suppression of HIF-1α-mediated glycolysis in hypoxia." (PMID 35563563, 2022). "Oncological research has reported that HIF-1α upregulation significantly promoted LDHA expression in bladder cancer cells." (PMID 35090526, 2022). "KDM3A has been reported to demethylate H3K9me2 on the promoter of glycolytic gene PGK, and it cooperated with HIF-1α to induce aerobic glycolysis in urinary bladder cancer." (PMID 35590288, 2022). "HIF-1α was shown to regulate the expression of UCA1 in bladder cancer cells by binding to two hypoxia responsive elements (HREs) in the promoter of UCA1, leading to its activation under hypoxic conditions." (PMID 34054950, 2021). "It has been shown that HO-1 overexpression promotes angiogenesis in urothelial carcinoma cells as well as in human pancreatic cancer; in bladder cancer, HO-1 overexpression correlates with HIF-1α and VEGF expression." (PMID 34067625, 2021). "In another study of bladder cancer, cisplatin-resistant cells exhibited higher levels of HIF1α, which was correlated with increased expression of MDR1 encoding the multidrug efflux pump P-glycoprotein (P-gp)." (PMID 34763667, 2021). "In our study, inhibition of PI3K/AKT and HIF-1α notably attenuated Vitamin K2-upregulated glycolysis, indicating that Vitamin K2 promotes glycolysis in bladder cancer cells via PI3K/AKT and HIF-1α signal pathways." (PMID 32382009, 2020). "Collectively, these results indicate that Vitamin K2 promotes PI3K/AKT and HIF-1α-mediated glycolysis in bladder cancer cells." (PMID 32382009, 2020). "In the present study, we have described for the first time that HIF-1α-mediated induction of miR-424 causes down-regulation of pro-apoptotic UNC5B and SIRT4, thereby inhibiting CDDP-dependent apoptotic cell death of bladder cancer cells." (PMID 32522234, 2020). "Vitamin K2 significantly induced the phosphorylation of PI3K/AKT, and increased HIF-1α expression in bladder cancer T24 cells in a time-dependent manner." (PMID 32382009, 2020). "In accordance with the previous observations, our present observations demonstrated that HIF-1α is required for CDDP-mediated transactivation of miR-424 in bladder cancer cells." (PMID 32522234, 2020). "The depletion of CIRBP using RNAi suppressed HIF1α levels to reduce the proliferation and migration of bladder cancer cell lines." (PMID 30717305, 2019). "A recent study has described a role for the cold-inducible RNA-binding protein (CIRBP) as a novel modulator of HIF1α translation in human bladder cancers." (PMID 30717305, 2019). "Some reports have demonstrated that hypoxia-inducible factor 1-alpha (HIF-1α), an indicator of hypoxia, is highly expressed in bladder cancer and that patients with high HIF-1α expression have poor prognoses." (PMID 30914736, 2019). "In the present study, we demonstrated that AE-AS is able to inhibit the angiogenesis in bladder cancer through suppressing HIF-1α induction and its-regulated pro-angiogenic signaling pathway." (PMID 28710377, 2017).
bladder cancer (continued). "Consistently, hypoxia-induced nuclear HIF-1α level and VEGF synthesis in T24 cells was greatly reduced by si-WSB-1, indicating that WSB-1 also stimulates the HIF-1α/VEGF cascade in bladder cancer." (PMID 28710377, 2017). "Findings suggest that HIF-1α is an important factor in the increase of bladder cancer cell permeability." (PMID 29267502, 2017). "Exosomal lncRNA-UCA1 RNA levels in the serum of bladder cancer patients were positively correlated with HIF-1α expression." (PMID 28841829, 2017). "Recently, it was shown that UCA1 transcription is induced by HIF-1α, to enhance hypoxic proliferation, migration and invasion of bladder cancer cells." (PMID 28715488, 2017). "Models of in vitro hypoxic cell culture of bladder cancer, bladder cancer cells with low HIF-1α expression and HIF-1α RNA interference (RNAi) expression vector were established." (PMID 29267502, 2017). "For instance, UCA1, which promotes EMT in bladder cancer cells, was found to be induced in bladder cancer cells under hypoxic conditions by the direct binding of HIF-1α to its promoter." (PMID 28430163, 2017). "In conclusion, our findings show that YBX acts as a tumor promoter by targeting Myc and HIF1α to facilitate glycolysis, which is crucial to the malignant phenotypes of bladder cancer cells." (PMID 29029484, 2017). "Myc and HIF1α are two crucial regulators in glycolysis and certainly contribute to the glycolytic phenotype of bladder cancer." (PMID 29029484, 2017). "This reverse post-translational regulation of HIF-1α protein by Foxp3 provides a new potential target for developing new therapeutic strategy for bladder cancer." (PMID 27557492, 2016). "In this study, we unveil a reverse regulatory mechanism contributing to bladder cancer progression; Foxp3 expression attenuates HIF-1α degradation." (PMID 27557492, 2016). "The results indicate that the increased expression of HO-1 in bladder cancer is paralleled by changes in the expression of other potentially interacting genes, like Nrf2, HIF-1α, HIF-2α, IL-6, IL-8, and VEGF." (PMID 26927195, 2016). "Among transcription factors affected by oxidative stress, and which are altered in bladder cancer, are hypoxia inducible factors (HIF-1α, HIF-2α), and Nrf2 transcription factor." (PMID 26927195, 2016). "Our results demonstrated that the Tet-inducible artificial microRNAs targeting β-catenin and HIF-1α can effectively inhibit malignant phenotypes of bladder cancer cells in a dosage-dependent manner." (PMID 26541358, 2015). "Our results demonstrated that the Tet-inducible artificial microRNAs targeting β-catenin and HIF-1α can be used to effectively silence the cancer-related genes and inhibit malignant phenotypes of bladder cancer cells in a dosage-dependent manner." (PMID 26541358, 2015). "In order to prove the utility of this platform, we chose β-catenin and HIF-1α as the functional targets and used the bladder cancer cell lines 5637 and T24 as the test models." (PMID 26541358, 2015). "Of interest is the observation that TP increased the hypoxic expression of HIF-1α in an orthoptic xenograft model of bladder cancer." (PMID 16317434, 2006). "Further studies are warranted to elucidate the transcriptional regulation of TIMP3 by HIF-1α and to validate its role in vivo, which may contribute to the advancement of targeted therapeutic strategies for bladder cancer." (PMID 41680285, 2026). "Notably, overexpression of TIMP3 reversed the alterations in bladder cancer cell behavior induced by HIF-1α knockdown." (PMID 41680285, 2026). "Notably, ALYREF was activated by HIF‐1α, thereby promoting glycolysis and the development of bladder cancer, suggesting its role in hypoxia during tumorigenesis." (PMID 40914946, 2026).
bladder cancer (continued). "In bladder cancer, the acquired mutation of isocitrate dehydrogenase 2 (IDH2) can induce reductive glutamine metabolism, stabilize the expression of HIF-1α, thus stimulate aerobic glycolysis and pentose phosphate pathway (PPP), and promote gemcitabine resistance." (PMID 41281744, 2025). "A study demonstrated that hypoxia in bladder cancer cells regulated the expression and localization of C/EBPα through a HIF-1α-dependent mechanism, which may be important for bladder cancer cell differentiation and proliferation." (PMID 38602556, 2024). "Furthermore, HIF-1α-induced activation of autophagy assumes a pivotal role in liver and bladder cancer cells." (PMID 38339408, 2024). "In bladder cancer, this pathway is hyperactivated and contributes to the metabolic reprogramming from oxidative phosphorylation to glycolysis, partly through increased HIF1α." (PMID 38339062, 2024). "The authors showed that in bladder cancer there was a positive correlation between HIF1A expression and both immune suppressive (PD-L1, Tregs, MDSCs, and M2 macrophages) and anti-tumour immune (CD8+ T cells, NK cells, M1 macrophages, and IFN response) gene signatures." (PMID 37240301, 2023). "It belongs to a CATH-FunFam that has low likelihood of exhibiting side effects, thus suggesting that HIF1A may represent a good drug target for bladder cancer." (PMID 35035776, 2022). "Moreover, MI markedly downregulated NF-κB and HIF-1α expression, suppressed bladder cancer cell proliferation, and induced bladder cancer cell apoptosis, thereby inhibiting bladder cancer development." (PMID 35293283, 2022). "MI efficiently inhibits bladder cancer progression both in vitro and in vivo by inhibiting the Nox4/NF-κB/HIF-1α signaling pathway by directly upregulating miR-26b expression, suggesting that MI might be a potential anticancer agent for bladder cancer." (PMID 35293283, 2022). "Furthermore, it has 7 putative bladder cancer drivers, including the hypoxia inducible factor HIF1A that triggers the coordination of chromatin regulating genes." (PMID 35035776, 2022). "Moreover, the concomitant expressions of YBX1 and HIF1α elevated the glycolytic capacity of bladder cancer cells." (PMID 34440660, 2021). "Apoptosis and autophagy of bladder cancer cells were downregulated by HIF-1α inhibitor YC-1." (PMID 33681390, 2021). "In NMIBC bladder cancers, HO-1 expression in tumor mass correlates with HIF-1α expression and microvessel density, and in particular, Nrf2 and HO-1 positivity correlates with HIF-1α, HIF-2α, and VEGF expression in the tumor, and with VEGF and interleukin levels in the plasma." (PMID 34067625, 2021). "Supporting this hypothesis, previous studies have shown that HIF-1α significantly increases in high-grade, invasive, and metastatic bladder cancer tissues compared with low-grade tumors." (PMID 34441434, 2021). "As a result, KDM3A promotes bladder cancer progression by enhancing glycolysis via coactivating HIF-1α and may serve as a potential target for bladder cancer treatment." (PMID 32354028, 2020). "Collectively, these findings reveal that Vitamin K2 could induce metabolic stress and trigger AMPK-dependent autophagic cell death in bladder cancer cells by PI3K/AKT/HIF-1α-mediated glycolysis promotion." (PMID 32382009, 2020). "In other words, current study suggests that combination chemotherapy with HIF-1a inhibition would target the normoxic bladder cancer cells, which may help to optimize conventional chemotherapy with HIF-1 inhibitors." (PMID 32522234, 2020).
bladder cancer (continued). "From the clinical point of view, it is highly likely that the combination chemotherapy of CDDP plus HIF-1α/miR-424 inhibition might have a significant impact on hypoxic as well as normoxic bladder cancer cells." (PMID 32522234, 2020). "In summary, the major novelty in this study is that Vitamin K2 is able to induce autophagic cell death in bladder cancer cells by establishing the metabolic signal axis: PI3K/AKT/HIF-1α dependent glycolysis promotion-metabolic stress-AMPK/ULK1 activation-mTORC1 pathway suppression." (PMID 32382009, 2020). "Notably, CDDP treatment induced miR-424 expression in a HIF-1α-dependent manner in bladder cancer 5637 cells." (PMID 32522234, 2020). "Taken together, our study indicated that CIRBP could be a novel oncogene in human bladder cancer inducing transcription of HIF-1α, which could inhibit expression of methylated PTGIS." (PMID 30315244, 2018). "We hypothesized that during hypoxia, an increase in the HIF-1α and VEGF protein expression would lead to an increase in bladder cancer cell permeability, and that HIF-1α is an important factor in the increase of bladder cancer cell permeability." (PMID 29267502, 2017). "To test whether Myc or HIF1α mediates the YBX1-induced glycolytic phenotype and cellular functions in bladder cancer, we introduced Myc and HIF1α to YBX1 knockdown cells." (PMID 29029484, 2017). "HIF-1α is an important factor in the increase of bladder cancer cell permeability." (PMID 29267502, 2017). "In this study, we showed that YBX1 could promote glycolysis in bladder cancer cells by modulating Myc and HIF1α expression, which further facilitate the expression of glycolytic enzymes and ultimately contribute to tumor progression." (PMID 29029484, 2017). "Moreover, we have set the molecular basis to comprehensively address the transcriptional programs and molecular nature of bladder cancer cells under hypoxia, as well as the role of HIF-1α, towards novel biomarkers and therapeutic strategies." (PMID 27835695, 2016). "Taken together, Foxp3 expression in tumor cells can suppress intratumoral immunity in bladder cancer, which might be mediated though HIF-1α and its downstream VEGF production." (PMID 27557492, 2016). "Future biochemical studies may be able to demonstrate the in situ co-localisation of miR-210 and HIF-1α in bladder cancer tissue, but this was beyond the scope of this current biomarker study." (PMID 27441495, 2016). "This is the first study to demonstrate that the angiogenic activity of LMWF in bladder cancer may be attributed to suppressing the HIF-1α/VEGF signaling pathway." (PMID 26193287, 2015). "Therefore, targeting HIF-1α or NLRP3 inflammasome components may represent a novel therapeutic strategy for bladder cancer treatment." (PMID 37715239, 2023). "Moreover, cisplatin resistance in bladder cancer was induced by activating autophagy under hypoxic conditions, which could be reversed by autophagy or HIF-1α inhibitors." (PMID 35931669, 2022). "Hence, VK2 could induce metabolic stress and trigger AMPK-dependent autophagic cell death in bladder cancer cells by PI3K/AKT/HIF-1α-mediated glycolysis elevation, this being one of the VK2-induced anticancer mechanism." (PMID 33917442, 2021). "Besides this, Nrf2 activation has also been shown to elevate HIF-1α in bladder cancer tissue." (PMID 34073079, 2021). "While prior research has highlighted HIF-1α expression as a promoter of angiogenesis and tumor invasion in bladder carcinoma and metastasis in uveal melanoma, our analysis suggests that a period of TMD-induced latency may also be compatible with hypoxia in these cancers." (PMID 34307377, 2021). "Additionally, in bladder cancer, HIF-1α promotes ZEB1 expression and EMT." (PMID 30541610, 2018).
bladder cancer (continued). "Moreover, bladder cancer tissues resistant to cisplatin treatment had higher levels of both of these proteins, and in vitro studies in bladder cancer cell lines demonstrated that increased HIF-1α levels enhanced MDR-1 expression and promoted cisplatin resistance." (PMID 28383481, 2017). "On the other hand, both FGFR signaling and VEGF signaling can be regulated by HIF-1α expression in bladder cancer, which may reduce the correlation of Foxp3 expression with tumor stage and grade, because both of two signaling represent divergent molecular pathways in urothelial carcinogenesis." (PMID 27557492, 2016). "Previous studies have reported that, P4HA2-mediated stabilization of HIF-1α promotes FGFR3 expression and increases erdafitinib resistance in bladder cancer." (PMID 40379610, 2025). "In this regard, it has been reported that increased levels of HO-1 are paralleled with the increased levels of HIF-1α and induction of its downstream target gene, VEGF, in bladder cancer." (PMID 38791428, 2024). "For example, METTL3 directly promotes the expression of hypoxia-inducible factor 1-alpha (HIF-1α), VEGFA and tyrosine kinase (TEK) in bladder cancer (BLCA)." (PMID 39098905, 2024). "In erdafitinib-resistant bladder cancer cells, high levels of prolyl 4-hydroxylase subunit alpha 2 (P4HA2) stabilize hypoxia inducible factor 1α (HIF-1α), which activates downstream target genes and lowers ROS levels in bladder cancer." (PMID 38982494, 2024). "It has been shown that hypoxia-regulated HIF-1α is correlated with the MDR1/P-gp expression in many cancer cell lines, such as breast, colon, and bladder cancer cells." (PMID 36551540, 2022). "For example, PLOD2 was regulated by hypoxia-inducible factor-1α (HIF-1α) to promote sarcoma metastasis; PLOD2 was regulated by miRNA-26a-5p and miR-26b-5p in bladder cancer." (PMID 36276118, 2022). "Serum copper and zinc levels are closely related to the expression of HIF1-α and VEGF in bladder cancer tissue, indicating that copper plays an important role in angiogenesis." (PMID 36620542, 2022). "Under a hypoxic microenvironment, activated NF-κB, concomitant with the switch of HIF-1α to HIF-2α, forces the malignant behavior of bladder cancer T24 cells." (PMID 34073079, 2021). "In human bladder cancer cells, CIRP has been shown to bind the 3′-UTR of HIF-1α mRNA, thereby increasing its stability and extending its translation." (PMID 34465343, 2021). "Previous studies have shown an increased expression of HIF-1α, VEGF-A, and other angio-genesis markers in bladder cancer." (PMID 33146980, 2021). "HO-1 expression is upregulated together with HIF-1α, HIF-2α and Nrf2 in bladder cancer in comparison to healthy tissue." (PMID 34073079, 2021). "In this study, we have found for the first time that cisplatin (CDDP) induces the expression of miR-424 in a HIF-1α-dependent manner under normoxia, and miR-424 plays a vital role in the regulation of CDDP resistance of bladder cancer cells in vitro." (PMID 32522234, 2020). "Taken together, Vitamin K2 triggers AMPK-dependent autophagic cell death in bladder cancer cells via PI3K/AKT and HIF-1α signal pathways." (PMID 32382009, 2020). "In the current study, we have found for the first time that miR-424, a direct target of HIF-1α, decreases CDDP sensitivity of bladder cancer cells through down-regulation of pro-apoptotic UNC5B and SIRT4." (PMID 32522234, 2020). "In conclusion, our study regarded Vitamin K2-upregulated glycolysis as a bridge to connect activation of PI3K/AKT and HIF-1α with metabolic stress, which triggers AMPK-dependent autophagic cell death in bladder cancer cells." (PMID 32382009, 2020). "Angelica acetone extract significantly reduced the expression of hypoxia-inducible factor 1-alpha (HIF-1-α) and vascular endothelial growth factor (VEGF) in bladder cancer cells, effectively reducing the formation of cancer microenvironment." (PMID 31636686, 2019).